HMCN1 (hemicentin 1)
Description:
Involved in transforming growth factor beta-mediated rearrangement of the podocyte cytoskeleton which includes reduction of F-actin fibers and broadening, flattening and elongation of podocytes. Plays a role in basement membrane organization (By similarity). May promote cleavage furrow maturation during cytokinesis in preimplantation embryos (By similarity). May play a role in the architecture of adhesive and flexible epithelial cell junctions (By similarity). May play a role during myocardial remodeling by imparting an effect on cardiac fibroblast migration (By similarity).
Synonyms: FIBL-6; FIBL6; FBLN6; ARMD1
Tractability: Antibody: its Gene Ontology location is reachable by antibodies, with high confidence; UniProt places it where antibodies can reach, with medium confidence; UniProt predicts a signal peptide or a membrane-spanning region. PROTAC: ubiquitination databases record sites on it.
Gene: Protein-coding gene on chromosome 1 (185,734,391 to 186,190,949, forward strand). Ensembl gene ENSG00000143341.
Subcellular location: Secreted, extracellular space, extracellular matrix, basement membrane; Cytoplasm; Cell junction; Cleavage furrow
Subcellular location (Human Protein Atlas): Cytosol; Golgi apparatus; Predicted to be secreted
Gene Ontology:
Molecular function: extracellular matrix structural constituent; protein binding; cell adhesion mediator activity; calcium ion binding
Biological process: actin cytoskeleton organization; basement membrane organization; heterophilic cell-cell adhesion; homophilic cell-cell adhesion
Cellular component: extracellular exosome; extracellular matrix; adherens junction; anchoring junction; basement membrane; cleavage furrow; cytoplasm; muscle tendon junction; non-collagenous component of basement membrane; non-collagenous component of interstitial matrix; plasma membrane; cell cortex; cell junction; extracellular region
Genetic constraint (gnomAD): Loss-of-function variants: 263 observed, 536.24 expected, observed/expected ratio (o/e) 0.49, 90% interval 0.44 to 0.54. The upper end of that interval is the gene's LOEUF score, 0.54, which puts it in group 2 of 6, group 1 being the genes least tolerant of losing a copy. Missense variants: 5,804 observed, 6,365.4 expected, observed/expected ratio (o/e) 0.91, 90% interval 0.89 to 0.93. Synonymous variants: 2,171 observed, 2,260.4 expected, observed/expected ratio (o/e) 0.96, 90% interval 0.93 to 1.
Homologues: Orthologues: chimpanzee HMCN1 (99% identical), macaque HMCN1 (98% identical), dog HMCN1 (91% identical), pig HMCN1 (90% identical), mouse Hmcn1 (87% identical), rat Hmcn1 (87% identical), guinea pig HMCN1 (84% identical), rabbit HMCN1 (79% identical), zebrafish hmcn1 (66% identical), tropical clawed frog hmcn2 (38% identical), Drosophila melanogaster bt (8% identical), zebrafish hmcn2 (7% identical), and 2 more. Paralogues in human: OBSCN (15% identical), SPEG (7% identical), IGFN1 (6% identical), MYPN (6% identical), ALPK3 (5% identical), PALLD (5% identical), CCDC141 (4% identical), MYOT (2% identical), SPEGNB (1% identical).
Diseases named in the same sentence as HMCN1 in open-access papers:
HMCN1 is named in the same sentence as 71 diseases in open-access papers, as found by Europe PMC text mining. Sharing a sentence is not in itself a finding about the gene and the disease. The quoted sentences say what the papers report.
age-related macular degeneration (13 papers, 2012 to 2025). Age-related loss of vision in the central portion of the retina (macula), secondary to retinal degeneration. "Of note, the HMCN1 variants associated with age-related macular degeneration are located in regions distinct from those harboring the EBS-associated variants." (PMID 39976600, 2025). "To date, hemicentin-1 has been implicated in the pathogenesis of age-related macular degeneration, post-infarction myocardial fibrosis, cancer, and kidney glomerular disease." (PMID 39976600, 2025). "HMCN1 is known to be associated with age-related macular degeneration, and polymorphisms within the HMCN1 gene are associated with diabetes in humans." (PMID 36134029, 2022). "Studies have shown that abnormal expression of HMCN1 is associated with age-related macular degeneration, tumorigenesis, Fraser syndrome, and cell fibrosis and glomerular disease." (PMID 36034861, 2022). "Variants of HMCN1 have been reported to associate with age-related macular degeneration, a phenotype that is characterized by extracellular deposits of proteins and lipids in the eye." (PMID 25338956, 2014). "Hemicentin 1 is implicated in age-related macular degeneration in humans and markers within and near HMCN1 have been reported to be strongly associated with VLDL levels (-log10P = 13.9) and aortic atherosclerosis (8.9)." (PMID 24586312, 2014). "Interestingly, a mutation in HMCN1 has been linked to occurrence of age-related macular degeneration." (PMID 37296840, 2023). "HMCN1 mutations have been reported to correlate with age-related macular degeneration." (PMID 34504132, 2021). "Mutations in HMCN1 are associated with age-related macular degeneration." (PMID 31834878, 2019). "HMCN1 mutations are believed to correlate with age-related macular degeneration." (PMID 30279964, 2018). "Previous studies suggest that HMCN1 is primarily associated with age-related macular degeneration (AMD)." (PMID 35886066, 2022). "Of note, polymorphisms in the HMCN1 gene, localized to the EGF domains, have been found to be associated with a higher propensity to develop age-related macular degeneration." (PMID 39976600, 2025). "Two of these genes have been related to ophthalmologic disorders, including age related macular degeneration (HMCN1) and keratoconus (VSX1) and several have been related to neurologic disorders (IKBKAP, SGCG, SACS, ARHGEF10, and CACNA1S)." (PMID 23139751, 2012). "However, HMCN1 is reported to be associated with age-related macular degeneration and therefore does not represent a strong candidate in comparison to the known pathogenic p.Arg76Ter variant in CLCNKB." (PMID 35668994, 2022).
breast carcinoma (10 papers, 2014 to 2024). "In analyzing pharmaceutically available genes in populations with different matrix molecular subtypes of breast cancer, four groups of subtype gene populations contained the gene HMCN1, which encodes immunoglobulin." (PMID 39493752, 2024). "HMCN1 was mutated in this study population of breast cancer; therefore, this gene can be used as a target for drug development in the future." (PMID 39493752, 2024). "Mutation of HMCN1 is associated with poor prognosis in clear cell renal carcinoma and breast cancer." (PMID 36645718, 2023). "The allelic mutation frequency of HMCN1 is also significantly related to the prognosis of breast cancer." (PMID 35886066, 2022). "Through a VAF-based analysis of mutations, we showed that VAFs of HMCN1 was possibly associated with breast cancer prognosis." (PMID 30279964, 2018). "There are at least three possible functional implications of the mutations in HMCN1 in breast cancer metastasis." (PMID 30279964, 2018). "Moreover, mutation of HMCN1 is associated with metastasis in breast cancer." (PMID 35735060, 2022). "Little research has focused on HMCN1 in breast cancer, but it is known that this gene is related to tumor heterogeneity and poor prognosis of BRCA." (PMID 35707265, 2022). "In conclusion, to our knowledge, this is the first study to identify HMCN1 as a potential metastatic factor in breast cancer using a comparative analysis of genomic and transcriptomic data registered in TCGA." (PMID 30279964, 2018). "In breast cancer, intratumoral heterogeneity of HMCN1 mutant alleles is associated with a poor patient prognosis, and mutations in HMCN1 occur in approximately 60% of patients, regardless of the MSI status in GC patients." (PMID 37215130, 2023). "We found that the Polyphen-2 score of nonsynonymous HMCN1 mutations did not significantly associate with breast cancer prognosis (PolyPhen-2 scores of < 0.85 vs. WT; P = 0.801 and PolyPhen-2 scores of ≥ 0.85 vs WT; P = 0.671)." (PMID 30279964, 2018). "Therefore, the HMCN1 VAF may indicate the metastatic potential of a breast cancer." (PMID 30279964, 2018).
gastric cancer (6 papers, 2021 to 2025). A primary or metastatic malignant neoplasm involving the stomach. "A study of molecular profiles and metastatic markers in Chinese gastric cancer patients indicated that samples carrying HMCN1 mutation are associated with peritoneal metastasis." (PMID 35886066, 2022). "As a cell polarity regulatory gene, HMCN1 is significantly up‐regulated in gastric carcinoma." (PMID 35735060, 2022).
Fraser syndrome (4 papers, 2015 to 2022). Fraser syndrome is a rare clinical entity including as main characteristics cryptophthalmos and syndactyly. "However, the absence of connective tissue defects in Hmcn1−/− mice indicates that loss of mammalian Hmcn1 does not lead to Fraser syndrome-like connective tissue defects, possibly due to functional redundancies with other fibulins." (PMID 34504132, 2021). "The generation of mutant Hmcn1 and Hmcn2 knock-in mouse models or the transgenic overexpression of mutant Hmcn1 and Hmcn2 variants may allow to test whether such dominant negative effects of mutant Hemicentins may phenocopy Fraser syndrome-like features in mice." (PMID 34504132, 2021). "Also, histological analysis of fetal and adult kidneys did not reveal any morphological differences, another phenotypic trait of Fraser syndrome, although the mutants lacked Hmcn1 normally present at the BM of renal epithelia and in the ECM around nephron progenitor cells and in renal stroma." (PMID 34504132, 2021).
ovarian carcinoma (4 papers, 2017 to 2022). A malignant neoplasm originating from the surface ovarian epithelium. "HMCN1 regulates cancer-associated fibroblasts (CAFs) to reinforce the aggressiveness of ovarian cancer." (PMID 35886066, 2022). "In ovarian cancer, HMCN1 may promote invasiveness by regulating cancer‐associated fibroblasts." (PMID 35735060, 2022). "Being an important component of ECM, HMCN1 has a significantly lower expression in multi-drug resistant ovarian cancer cells." (PMID 35886066, 2022). "Previous studies have revealed the function of CSMD3 in dendritic cells and regulation of HMCN1 in fibroblasts, suggesting these genes may regulate various components of the ovarian cancer microenvironment." (PMID 35735060, 2022). "Upregulation of fibulins (EFEMP1 and HMCN1), which bind EGFR and regulate cell adhesion and migration, correlates with tumour progression and poor prognosis in ovarian cancer." (PMID 28341962, 2017).
macular degeneration (3 papers, 2013 to 2022). Loss of vision in the central portion of the retina (macula), secondary to retinal degeneration. "The function of Fib3 is unknown, but related proteins, Fibulins2, 4, and 5, have been implicated in TGFβ binding to ECM and both Fibulin5 and Fibulin6 (hemicentin 1) are also loci for macular degeneration risk." (PMID 23840815, 2013). "In eight sporadic cases, we detected eight heterozygous rare sequence variants in six macular degeneration genes (CFH; FBLN1, OMIM 135820; FBLN3/EFEMP1, OMIM 601548; FBLN5, OMIM 604580; HMCN1, OMIM 608548; FBN2, OMIM 612570)." (PMID 27007659, 2016). "Furthermore, miRNA hsa-29a-3p plays a role in structure regulation, specifically regulating the synthesis of different collagen chains, and HMCN1 (hemicentin 1) is involved in macular degeneration and C1QTNF6 (C1q and TNF related 6) is involved in identical protein binding activity." (PMID 36114255, 2022).
myocardial infarction (3 papers, 2017 to 2022). Gross necrosis of the myocardium, as a result of interruption of the blood supply to the area, as in coronary thrombosis. "The results showed that the myocardial infarction size in ARS + miR-29b-3p inhibitor + si-HMCN1 group was significantly smaller than that in the ARS + miR-29b-3p inhibitor group." (PMID 36034861, 2022).
sarcoma (3 papers, 2022 to 2025). A usually aggressive malignant neoplasm of the soft tissue or bone. "Specifically, HMCN1 gene amplification was primarily observed in cholangiocarcinoma, while deep deletions and structural variants were more prevalent in sarcoma." (PMID 41458588, 2025). "Although MDN1, HMCN1 and LAMA2 mutation were universally present and significantly different among the three groups, up until now there was no study had reported the mutation of these three genes in any kind of sarcoma." (PMID 36153483, 2022).
cervical cancer (2 papers, 2018 to 2022). A primary or metastatic malignant neoplasm involving the cervix. "HOXD9 is upregulated in cervical cancer species, is strongly associated with metastasis rate and poor prognosis in cervical cancer patients, and stimulates the migration and invasive ability of cervical cancer cells by positively regulating HMCN1 levels." (PMID 36213580, 2022). "In cervical cancer from TCGA, however, survival time between the two groups of HMCN1 VAF values were also significantly different." (PMID 30279964, 2018).
colorectal cancer (2 papers, 2022 to 2023). A primary or metastatic malignant neoplasm that affects the colon or rectum. "HMCN1 is frequently mutated in prostate cancer and gastric and colorectal cancer." (PMID 36645718, 2023).
diabetic nephropathy (2 papers, 2022 to 2024). "In regards to kidney disease, HMCN1 variants play a role in renal pathophysiology and are considered as a potential gene causing diabetic nephropathy in Mexican Americans." (PMID 35886066, 2022).
glioblastoma (2 papers, 2025). The most malignant astrocytic tumor (WHO grade IV). "The results showed that HMCN1 mRNA expression was significantly elevated in cancers such as glioblastoma multiforme (GBM), skin cutaneous melanoma (SKCM), and kidney renal clear cell carcinoma (KIRC)." (PMID 41458588, 2025).
glioma (2 papers, 2019 to 2024). A benign or malignant brain and spinal cord tumor that arises from glial cells (astrocytes, oligodendrocytes, ependymal cells). "The mutation of HMCN1 and MUC17 may induce the increased cytolytic activity of glioma." (PMID 31428092, 2019).
hepatocellular carcinoma (2 papers, 2022 to 2023). A malignant tumor that arises from hepatocytes. "In hepatocellular carcinoma, HMCN1 protein was also found to be overexpressed in tumors by proteomic analyses." (PMID 35886066, 2022).
Alzheimer disease (1 paper, 2025). A progressive, neurodegenerative disease characterized by loss of function and death of nerve cells in several areas of the brain leading to loss of cognitive function such as memory and language. "Hmcn1, encoding an extracellular protein involved in epithelial cell junction organization, has been implicated in Alzheimer’s disease pathways." (PMID 40806623, 2025).
bone cancer (1 paper, 2025). A primary or metastatic malignant neoplasm affecting the bone or articular cartilage. "The results suggested that HMCN1 expression was highest in bone cancer cell lines." (PMID 41458588, 2025).
cervical squamous cell carcinoma (1 paper, 2018). A squamous cell carcinoma arising from the cervical epithelium. "In the 15 types of cancer, only cervical squamous cell carcinoma and endocervical adenocarcinoma (CESC) samples showed significantly poorer OS in the samples with higher HMCN1 VAFs (n = 7, VAF ≥ 0.30) than those with lower VAFs (n = 15, VAF < 0.30) (log-rank test: P = 0.048)." (PMID 30279964, 2018).
clear cell carcinoma (1 paper, 2022). "CAFs in high-grade plasmacytoid carcinoma and clear cell carcinoma tissues show an upregulation of HMCN1, and tumor cells tend to be less invasive after silencing HMCN1 expression in fibroblasts." (PMID 35886066, 2022).
cyst (1 paper, 2014). A sac-like closed membranous structure that may be empty or contain fluid or amorphous material. "For example, localization of HMCN1 protein in the cyst’s samples would be shown with immunohistochemical method." (PMID 25338956, 2014).
epidermoid cyst (1 paper, 2014). "The present study, by combining linkage and exome analyses, identified HMCN1 as a genetic causality of splenic epidermoid cyst." (PMID 25338956, 2014). "In the current study, taking the advantage of linkage and exome analyses, we demonstrated that variants of HMCN1 are strong candidates for the causality of splenic epidermoid cyst." (PMID 25338956, 2014). "One more example is using a forward genetic approach to knock out Hmcn1 from mouse and if such experiment showed a phenotype similar to splenic cyst, this will clearly enforce the hypothesis of HMCN1 involvement in splenic epidermoid cyst etiology." (PMID 25338956, 2014). "The molecular mechanism by which HMCN1 is likely involved in splenic epidermoid cyst still remains unknown." (PMID 25338956, 2014). "Considering that splenic epidermoid cyst has a structure filled with fluids and lined by a layer of epithelial cells, these phenotypic similarities with the previous observations would support the possible involvement of HMCN1 in the etiology of splenic epidermoid cyst." (PMID 25338956, 2014).
gallbladder cancer (1 paper, 2018). "According to another recent report, HMCN1 acts as a suppressor of gallbladder cancer metastasis and is commonly mutated in certain samples of head and neck squamous cell carcinoma." (PMID 30279964, 2018).
Hyperglycemia (1 paper, 2022). An increased concentration of glucose in the blood. "In vitro and in vivo models reveal that HMCN1 contributes to the remodeling of the podocyte cytoskeleton and the increased expression of HMCN1 in podocytes can be stimulated in response to hyperglycemia, which is an important risk factor of RCC." (PMID 35886066, 2022). "However, the correlation between hyperglycemia, the expression of HMCN1, and the development of ccRCC is not yet clear." (PMID 35886066, 2022).
lung adenocarcinoma (1 paper, 2022). A carcinoma that arises from the lung and is characterized by the presence of malignant glandular epithelial cells. "In addition, Hmcn1 and Lrp2 were previously reported as mutated in KRASG12DTP53null mouse lung tumours and are frequently mutated in human lung adenocarcinoma (13-16% in TCGA PanCancer Atlas), but are not considered as mutational drivers." (PMID 34779486, 2022).
melanoma (1 paper, 2019). A malignant, usually aggressive tumor composed of atypical, neoplastic melanocytes. "HMCN1 is also induced by Tris DBA HANP and high-level expression of this molecule is associated with improved prognosis in human melanoma." (PMID 30824801, 2019).